ERBB2 (erb-b2 receptor tyrosine kinase 2)
Diseases named in the same sentence as ERBB2 in open-access papers (continued):
Sharing a sentence is not in itself a finding about the gene and the disease.
tumor (continued). "Co-targeting ERBB2 and IGF1R reduces Erk/AKT activation, cell proliferation, in vitro invasion, and xenograft tumor growth to a greater extent than targeting either receptor individually." (PMID 25964777, 2015). "Follow-up studies revealed that BCAR4 mRNA levels correlate with tumor aggressiveness in advanced stage BCs and that BCAR4 acts in an ERBB2/3-dependent manner in ZR-75-1 and MCF7 cells." (PMID 26317614, 2015). "Evaluating with Oncomine data, we found most target genes (BCL2, ERBB2/3, SIRT7, ETS1, Mcl-1, IL6R, and LIN28B) were significantly activated in HCC tumor tissues, consistent with miR-125b underexpression." (PMID 25861255, 2015). "Activation or overexpression of ErbB such as ErbB2 (HER2) and ErbB3 (HER3) and EGFR has been observed in various types of tumours." (PMID 25977926, 2015). "Lapatinib, a clinically approved EGFR/ERBB2 inhibitor, counteracts BCAR4-driven tumor cell growth, a clinical relevant observation." (PMID 26317614, 2015). "We observed that ErbB2, MRP1 and MRP2 expression significantly differed (***p < 0.001) with ErbB2 and MRP1 increased in tumor tissues whereas MRP2 mRNA level was reduced." (PMID 25890497, 2015). "In addition we found that, presence of EGFR instead of ErbB2 in the triple oncogene combination potentially drives an early lung metastasis and give unique liver metastasis from same cellular precursor i.e K5+/K19− suggesting the significant effect of an oncogene on pathogenicity of tumor." (PMID 25940703, 2015). "However, the two parameters interact with respect to their association with the tumour stage; and 3) that ErbB2 is not a clinically useful prognostic marker for predicting disease-specific survival as adjudged by its performance in the tissue microarray used here." (PMID 25215939, 2014). "Targeting ERBB2 with lapatinib in combination with the BRAF inhibitor PLX4720 reduced tumor burden and extended latency of tumor regrowth in vivo versus PLX4720 alone." (PMID 24743024, 2014). "Comparison of gene expression in Set 1 with the Sanger COSMIC dataset identified five down-regulated genes that have previously been confirmed to result in neoplasia; these included CEBPA, ERBB2, EXT1, PIM1, and SDHD." (PMID 25023465, 2014). "We found that high ZNF217 expression consistently predicted poor prognosis across multiple tumor subtypes: Luminal, ER−, HER2+/ERBB2+, and basal cohorts." (PMID 24962896, 2014). "In the present study, we have investigated whether tumour ErbB2 immunoreactivity (ErbB2-IR) has clinically useful prognostic value, i.e. that it provides additional prognostic information to that provided by routine clinical tests (Gleason score, tumour stage)." (PMID 25215939, 2014). "Although there are limited prior molecular studies of SDC, many of these studies have suggested that overexpression of epidermal growth factor receptor 2 (ERBB2, also known as HER2) is a common event in this tumor type." (PMID 25343854, 2014). "The data suggests that in the setting of ERBB2 amplified cancers, overexpression of ERBB2 leads to constitutive ligand-independent heterodimerization with ERBB3 and activation of downstream signaling events that promote tumor progression." (PMID 25386657, 2014). "Epidermal growth factor receptor belongs to the ErbB family of tyrosine kinase receptors, which includes EGFR (ErbB-1), HER-2/neu (ErbB-2), HER-3 (ErbB-3), and HER-4 (ErbB-4), all known to be involved in modulating pathways of tumor growth or proliferation." (PMID 24945674, 2014). "In contrast, in RKO tumor cells treated with the TRAIL plus 17-AAG combination, Z-IETD-FMK exposure resulted in the levels of depleted HSP90 client proteins such as ERBB2, IKKα and AKT returning to those observed in tumor cells treated with 17-AAG alone." (PMID 23852390, 2013). "SUM190, derived from a primary tumor, is the only other human cellular model for IBC representing an ErbB2 overexpressing, ERneg cell line." (PMID 23341929, 2013).
tumor (continued). "EGFR and ERBB2 were also both found to be significantly up-regulated in all r4 subgroups as well as in the GNB and GN tumours." (PMID 23835063, 2013). "A similar phenomenon has been described for other RTKs such as EGFR, ErbB2, ErbB3, ErbB4 and VEGFR2 where truncated versions had functional implications for the growth of the tumor cells." (PMID 24205204, 2013). "More specifically, we focused on a select number of SATB1 target genes that are known to participate in tumorigenesis and metastasis (e.g. tumor/metastasis suppressors BRMS1, Kiss1, Claudin-1; tumor/metastasis promoters c-Abl, MMP3, ErbB2 and Snail)." (PMID 24260116, 2013). "Analysis of gene expression in fibroblasts revealed a tumor- and Ets2-dependent gene signature that was enriched in genes important for ECM remodeling, cell migration, and angiogenesis in both PyMT and ErbB2 driven-tumors." (PMID 23977064, 2013). "We conclude that the ERBB-profile (high expression of EGFR, ERBB2 and ERBB3) defines a ganglion-rich neuroblastic tumour sub-set." (PMID 23835063, 2013). "ErbB family member genes (ERBB-genes; EGFR, ERBB2, and ERBB3) and 15 previously reported tumour suppressor candidate genes (TS-genes) were next studied by heat maps in all four data sets." (PMID 23835063, 2013). "We tested the effect of TMI-1 on luminal, basal and ERBB2-overexpressing breast tumor cell lines and on MMTV-ERBB2/neu tumor evolution." (PMID 23028451, 2012). "A significant reduction of tumour size was also observed in tumours derived from EV9 (0.55±0.17) and EV18 (0.18±012) ErbB2-KD cells when compared to NT controls (1±0.1, **, p = 0.017)." (PMID 22393391, 2012). "One possible explanation for this difference is that the tumour-initiating cell population in the PyVmT model is absolutely reliant on FAK, whereas this population in the ErbB2 model can function independently of FAK signalling." (PMID 22373082, 2012). "Tumor cells from ascites or solid tumor specimens were enriched by magnetic depletion of CD45+ leukocytes and assessed for relative ERBB2 mRNA levels via q-PCR." (PMID 23189165, 2012). "Bioinformatic analysis of mRNA targets of the altered miRNAs, identified oncogenes like ERBB2, YY1, several MAP kinases, and known tumor-suppressors like FOXA1 and SMAD4." (PMID 22438871, 2012). "Next we compared the ERBB2 mRNA and protein levels in normal OSE cells, malignant primary ascites and solid tumor-derived tumor cells." (PMID 23189165, 2012). "The results showed that tumours derived from both genotypic combinations expressed elevated levels of FAK and ErbB2." (PMID 22373082, 2012). "RAC1 was significantly higher and associated with poor prognosis in HER2 (ERBB2) over-expressing tumours, although the range of RAC1 expression was similar between HER2+ and HER2− tumours." (PMID 22689141, 2012). "Other investigators have shown that leptin indirectly transactivates erbB2 and stimulates epidermal growth factor (EGF) receptor phosphorylation in tumor cells." (PMID 21533119, 2011). "Coexpression of Brk and ErbB2 in human (MCF-10A) or murine (Comma-1D) mammary epithelial cells induced acinar disruption and increased tumor growth, respectively." (PMID 21923922, 2011). "Although lapatinib is a more potent inhibitor of ErbB-2 activity in vitro compared with trastuzumab, trastuzumab is more efficient in inhibiting BT474 tumour growth." (PMID 21847123, 2011).
tumor (continued). "Primary tumor microarray (TMA) cores were analyzed for 17 proteins using immunohistochemistry and for erbB2 using chromogenic in situ hybridization, and their associations with the first metastasis site were examined." (PMID 21914172, 2011). "In advanced tumours, EGFR, ERBB2 and ERBB3 upregulation is common and there is a relationship between expression of ERBB2 and ERBB3 but not the NRG1 ligand." (PMID 21364580, 2011). "In summary, ERBB2 and EGFR are transmembrane tyrosine kinases that can promote tumorigenesis and tumor progression." (PMID 21689422, 2011). "At present, pathological examination is primary method used to assess the ERBB2 and EGFR status of tumor cells." (PMID 21689422, 2011). "Lapatinib also exhibited antitumor activity in these ErbB2-overexpressing tumor models, but AST1306 was more efficacious than lapatinib in the SK-OV-3 xenograft tumor model when given at the same dose and schedule." (PMID 21789172, 2011). "Given the inverse correlation between BRCA1 and ErbB2 levels in tumours, it was expected that some component of the NRF-1 > GABP > BRCA1 pathway would be sensitive to ErbB2-overexpression." (PMID 21609478, 2011). "Further, we determined binding of CL4 on stable tumor derived cell lines that differently express EGFR family members (EGFR, ErbB2, ErbB3, or ErbB4)." (PMID 21915281, 2011). "The high level of erbB2 expression makes the SKOV3ip1 model appropriate to test our double-targeting strategy, which engages both mechanisms of MSC-AR tumor targeting: native and engineered." (PMID 20500878, 2010). "For example, ErbB2 and ErbB3 cooperate to promote MMTV-Neu induced tumorigenesis, and activation of AKT and MAPK downstream of ErbB2/ErbB3 affects tumor cell proliferation." (PMID 20860838, 2010). "In tumor cell lines and xenograft models, lapatinib has inhibited EGFR and p-ErbB2, p-Erk1/2, p-AKT, and cyclin D, and this effect was dose and time dependent." (PMID 21050422, 2010). "The amplification frequency of the BAC clone harboring ERBB2/HER2 was in 41.7% of the cell lines and 17.1% of the tumor tissues." (PMID 20070913, 2010). "ErbB2 was overexpressed in our RM11A cell line, a murine tumor cell line that overexpresses human IGF-IR in an inducible manner." (PMID 20825649, 2010). "ERBB2 and CCR1 were genes activated in late EECs, while APBA2 (MINT2) and CDK inhibitor p16 tumor suppressors in early EECs." (PMID 20015385, 2009). "c-ErbB2 tumours demonstrate overexpression of EGFR, ErbB2, ErbB3 and ErbB4, and activation/phosphorylation of both ErbB2 and ErbB3, underscoring the importance of the entire EGFR family in ErbB2-induced tumourigenesis." (PMID 18700973, 2008). "To model the effects of ErbB2‘+’/ErbB3‘+’ normal tissue on ALM targeting, we used fluorescently labelled MCF10a normal breast epithelial cells mixed with unlabelled BT-474 tumour cells." (PMID 18841159, 2008). "Nevertheless, PCGF2 and PSMB3 are rarely amplified with ERBB2 in tumors, and PCGF2 has been reported to be a tumor suppressor." (PMID 17584934, 2007). "Three genes in this pathway had IRs >2 in our set of 47 primary tumors; EGFR in two tumors, ERBB2 in three tumors, and GRB2 in one tumor." (PMID 16457699, 2005). "In parallel, we had also tested our tumour DNAs for amplification of CCND1, ERBB-2 and MYC, which made it possible to test for correlations with 20q13 or MDM2 amplifications." (PMID 8980401, 1996). "Primary tumours and cell lines expressed EGFR, showing higher basal level phosphotyrosine staining than erbB-2." (PMID 7599067, 1995).
tumor (continued). "Some CNAs overlapped between tumor types, others were tumor type-specific; losses of CDH20 and PTEN were observed in both tumor types, whereas amplifications seemed more tumor type-specific, such as EGFR and MAP2K4 in colon cancer and ERBB2 in breast cancer." (PMID 41537310, 2026). "The expression levels of growth factor receptor genes (EGFR and ERBB2) and proliferation marker genes (PCNA and MKI67) in epithelial cells were not significantly higher in unaffected lung samples adjacent to a focal tumor compared with samples originating from healthy lungs." (PMID 40114924, 2025). "On the other hand, in two tumor progression models using the MCF-10A.B2 cell line, which overexpresses ERBB2, and the MCF-10A.B2Cas cell line, which overexpresses the p130Cas protein, differential miRNA expression was observed in 3D cultures embedded in Matrigel® compared to 2D cultures." (PMID 41375031, 2025). "The results indicated that IHC staining for PR and ErbB2 was negative in the original CMGT_071020 tumor." (PMID 40689167, 2025). "We also compared tumor mutational burden (TMB) and fraction genome altered (FGA) in urothelial cancers with and without ERBB2 alterations." (PMID 41422272, 2025). "The human epidermal growth factor receptor 2 (HER2; also known as HER-2/neu or ErbB2) is a member of the transmembrane epidermal growth factor receptor family and is one of the most studied tumor-related antigens in tumor immunotherapy." (PMID 40438111, 2025). "All patients with ERBB2-positive or hormone receptor-negative DCIS experienced at least a partial response, with one-third experiencing complete resolution of the tumor, and high-baseline immune cells were associated with response." (PMID 40332761, 2025). "In contrast, in the absence of an intact immune system in NSG (NOD scid gamma) mice, WT and ERBB2 KO tumors showed similar growth behavior indicating that ERBB2 KO does not affect intrinsic tumor cell proliferation." (PMID 41361170, 2025). "Notably, the patient’s original pathology of the primary tumor was found to be HER2-negative, though a copy number gain of ERBB2 was detected in CSF tDNA several years later." (PMID 41149070, 2025). "LCN2 levels can be stimulated by increased Her2 (also known as ERBB2) activity and an increase in p38 (also known as MAPK) activity, and both lead to increased invasion and tumor formation." (PMID 40356520, 2025). "FoundationOne next-generation sequencing showed that her PD-L1 tumor proportion score was 0%, tumor mutation burden was low, and there were no reportable alterations in BRAF, ERBB2, KRAS, or NRAS." (PMID 40026534, 2025). "Notably, several genes involved in cell cycle regulation (CCND2, CDKN2A/C), tumor microenvironment (COL3A1, COL1A1), and growth factor signaling (FGF18, ERBB2) showed significant upregulation with fold changes ranging from 1.5 to 2.0." (PMID 41419500, 2025). "ctDNA can detect ERBB2 amplification in many, but not all, patients with ERBB2 amplification detected in tumor samples." (PMID 40512191, 2025). "For example, although 72 (61.5%) mutations, including an oncogenic RB1 S249* mutation, were shared between the SMBO-109 PDO and the tumor from which it was derived, ERBB2 amplification was present only in the organoid line but not in the tumor." (PMID 41422272, 2025).
tumor (continued). "The ERBB2 gene is a member of the epidermal growth factor receptor (HER) family and is related to a variety of cell signaling pathways that play important roles in cell proliferation, tumor formation, and apoptosis." (PMID 40842594, 2025). "The most common tumor receptor subtype was HR positive and ERBB2 negative (64.8%), followed by HR positive and ERBB2 positive (6.2%), HR negative and ERBB2 negative (4.9%), and HR negative and ERBB2 positive (1.9%)." (PMID 39946126, 2025). "ERBB2 (HER2), a receptor tyrosine kinase frequently dysregulated in breast and other cancers, also appears as a DDR1 interactor, suggesting a possible cooperative role between DDR1 and RTKs in promoting tumor cell proliferation and survival." (PMID 40869052, 2025). "Meanwhile, the original tumor of CMGT_180321 was positive for all tested receptor protein markers, except ERα and ErbB2 were negative." (PMID 40689167, 2025). "The estimated ERBB2 total copy number was similar between the PDO models and the tumors from which they were derived, with the notable exception of SMBO-109 (ERBB2 copy number of 13 for the PDO and 5 for the tumor)." (PMID 41422272, 2025). "Patients who had ERBB2 amplification detected on ctDNA had significantly higher mean VAF compared with those who did not have ERBB2 variation detected, suggesting that lack of detection is at least in part a result of low tumor shedding." (PMID 40512191, 2025). "We found that CSCs expressed high levels of tumor stemness genes (PROM1, CD24, CD47, ANPEP, ALDH1A1, OLFM4, and SOX9), and demonstrated a high cancer stemness score, along with activation of the cancer driver genes EGFR and ERBB2." (PMID 39950944, 2025). "Three hundred forty-six patients were enrolled in the HER2 cohort of MyPathway with protocol-stipulated HER2 molecular alterations [reference MyPathway Protocol V4, V5] and 85 were enrolled with ERBB2-amplified and/or -overexpressing CRC based on local tumor analysis." (PMID 40512191, 2025). "In contrast, AI resistance—which affects over 20% of early-stage and most metastatic cases—is driven by both intrinsic (e.g., upregulation of FGFR, ERBB2, IGF1R, PI3K-AKT-mTOR, MAPK signaling) and extrinsic factors, including interactions with the tumor microenvironment." (PMID 40641933, 2025). "Moreover, Src frequently interacts with multiple growth factor receptors, such as EGFR, HER2/ErbB2, PDGFR, IGF-1R, and c-Met/HGFR, further enhancing downstream signalling and transcriptional activity that drive tumour growth and disease progression." (PMID 41155542, 2025). "Combined treatment with ASOs and trastuzumab in organoids, as well as with vivo-MO and T-DXd in PDX models, significantly inhibited tumor cell growth, highlighting that combined therapy can improve the anti-ERRB2 targeting efficacy, particularly in overcoming ERBB2 resistance." (PMID 39948369, 2025). "To control for unanticipated effects of TAM on tumor growth, we also examined tumor growth in Erbb2/Cre/Pfkfb3+/+ mice (WT for Pfkfb3) with and without TAM administration and observed similar growth in both groups." (PMID 39001392, 2024). "The proliferation of tumor cells is primarily driven by TKRs, including members of the ERBB family (such as ERBB1/EGFR, ERBB2/HER2) and insulin-like IGF-1R, which activate oncogenic signalling pathways, including the PI3K/Akt/mTOR and MAPK/ERK pathways when overexpressed." (PMID 39199143, 2024).